IFNG (interferon gamma)
Diseases named in the same sentence as IFNG in open-access papers (continued):
Sharing a sentence is not in itself a finding about the gene and the disease.
glioma (continued). "Do presented a study on tumor necrosis factor alpha (TNF-alpha) and interferon gamma (IFN-gamma) induced NO production in glioma cells." (PMID 22072995, 2011). ",12 (R)-2HG in the TME may impair production of IFNγ and IL-2 by CD4+ and CD8+ T cells as well as impacting myeloid cell populations, for example immunosuppressive glioma-associated macrophages generated due to altered tryptophan metabolism." (PMID 41138165, 2025). "Similarly, increased TIM-3 expression and decreased IFNγ expression were demonstrated in tumor-infiltrating CD8+ T cells in a syngeneic glioma mouse model, although potential changes in BAT3, FOXO1, BLIMP1, and CD69 expression were not reported in this study." (PMID 39513882, 2024). "However, CD8+ TILs that have been detected in glioma and colon cancer showed increased activation and cytotoxicity, as indicated by elevated levels of interferon gamma (IFN-γ), tumor necrosis factor alpha (TNF-α), and IL-2 protein or RNA synthesis." (PMID 39537934, 2024). "Inhibition on the IFNG-triggered JAK/STAT pathway can prevent glioma invasion and tumorigenesis." (PMID 37122693, 2023). "The improved survival rate of S100a4−/− glioma-bearing mice was associated with the generation of anti-tumor immunity, accompanied by increased phagocytic activity of CD11b+ glioma-associated myeloid cells and enhanced activity of CD4+ T cells, stimulating T cell proliferation and IFNγ secretion." (PMID 38274827, 2023). "The antitumor cytotoxic T cell activity of T-αFGL2 cells against the FGL2-expressing murine glioma cell line, DBT, was evaluated by measuring the proportion of live glioma cells and granzyme B+, interferon γ (IFNγ)+, and tumor necrosis factor α (TNFα)+ T cells." (PMID 36759517, 2023). "IFNγ upregulation implicates the alteration of glioma microenvironment." (PMID 35646111, 2022). "Interferon Gamma (IFN-γ) is a soluble dimer cytokine involved in immune escape of gliomas." (PMID 36712869, 2022). "IFNG is a double-edged sword immune-modulator and its role in glioma remains controversial." (PMID 35492352, 2022). "For instance, the immune cytolytic activity measuring the function of CD8+ T cell, and the IFNG response genes indicating activation of adaptive immune responses were negatively correlated with the overall survival of glioma patients, which is in line with our findings." (PMID 35492352, 2022). "Among them, most of the HLA, checkpoints, chemokines, costimulatory molecules, IFNG, CD8, and CD274 were highly expressed in the high-risk group, which showed that the high-risk group may get more chances from the anti-glioma immunotherapy." (PMID 36466844, 2022). "All of these results suggest that APOBEC3 upregulation in low grade glioma can stimulate macrophages through interferon gamma and activation of myeloid-derived cells, leading to tumor immune response and accelerating tumor cell immune escape by upregulating immune checkpoints." (PMID 34638749, 2021). "BDNF stimulates the production of Interleukin-15 (IL-15) in the brain of glioma-mice, and IL-15, in turn, stimulates natural kill (NK) cells to produce Interferon-gamma (IFN-γ) that affects the phenotype of myeloid cells, promoting the transition to an anti-tumour state." (PMID 34489641, 2021). "Similarly another proinflammatory cytokine IFNγ, produced by NK, DC, and T-cells diminishes the invasive phenotype of glioma cells by inhibiting its interactions with extracellular matrix molecules." (PMID 33790740, 2021). "GSEA showed that the coexpressed positive genes associated with ANXA1 were mainly involved in immune-related functions, such as interferon-gamma response and regulation of innate immune response, suggesting a regulatory role in the immune microenvironment in gliomas." (PMID 34912807, 2021). "Also they observed an increased infiltration of T cells, DCs and M1 macrophages; and an increased sensitivity of glioma cells to IFNγ-induced apoptosis." (PMID 34168976, 2021).
glioma (continued). "Interestingly, the combination of IFNγ and TMZ that mimics the in vivo situation led to similar or even stronger IDO1 upregulation compared to IFNγ alone in two out of four glioma samples." (PMID 32117235, 2020). "Nevertheless, we found reduced IFNγ positive staining in the glioma area." (PMID 32668709, 2020). "Notably, cell targets with low surface EGFR expression relative to A431 were also efficiently lysed, although production of IL-2, TNFa and IFNg was lower when glioma cell lines were used as targets compared to A431." (PMID 31903167, 2019). "In addition to a modulation of TAM phenotype, we observed that LPS/IFNγ-MV affect glioma cell properties." (PMID 30853898, 2019). "We wonder whether the interaction of MVs with TAMs could modulate their pro-tumor activity, and investigated the effect of LPS/IFNγ-MV on gene expression of CD11+ cells isolated from the brains of glioma-bearing mice." (PMID 30853898, 2019). "Furthermore, inhibitory effect of verbascoside on neuronal nitric oxide synthase expression in lipopolysaccharide/interferon-gamma induced inflammation in glioma cells has been reported." (PMID 28884085, 2017). "IFNγ inhibits proliferation, migration and angiogenesis in glioma." (PMID 26390214, 2015). "We identified seven cytokines from previous glioma or allergy literature (IL4, IL13, IL5, IL6, IL10, IFNG and TGFB2) to determine whether, they were associated with glioma before diagnosis." (PMID 26352148, 2015). "We have previously shown that CM harvested from glioma cells under basal conditions (C-CM), as well as CM from glioma cells activated with LPS/IFNγ (LI-CM), increased the phosphorylation of mTOR at ser 2448, an index of mTORC activation, in microglial cells in 2-h experiments." (PMID 25051975, 2014). "Leptin has been shown to induce or to potentiate together with interferon γ (IFNγ), with tumor necrosis factor α (TNFα) or with IFNγ and IL-1β, NO production in murine J774A.1 macrophages, rat adipocytes, C6 glioma cell-line, and rat vascular smooth muscle cells (VSMCs)." (PMID 19688109, 2009). "Additionally, enhanced IFN-γ expression accompanied with TNFRSF14 elevation (High-IFNG & High-TNFRSF14) indicated a shorter survival in glioma than the lower counterpart (Low-IFNG & Low-TNFRSF14), while similar results couldn’t be obtained from PD-L1." (PMID 39085878, 2024). "Although various IFNG-related inflammatory responses may be active in the glioma microenvironment with elevated IFNGR scores, macrophages with increased expression of IFNGR1 and IFNGR2 were preferentially subject to transcriptional regulation by NF-κB and STAT3." (PMID 35492352, 2022). "A gene ontology analysis suggested a correlation of inflammatory response, immune response, and IFNγ-mediated signaling pathway with higher Arid5a expression in glioma, which may further reveal mechanisms that affect the growth, and proliferation of cancer cells." (PMID 35126382, 2021). "We demonstrated that LPS/IFNγ-MV, which contain the transcripts for a number of inflammation-related genes, can modify TAMs phenotype reducing the expression of anti-inflammatory genes, exert protective effects on neurons and reduce glioma cell proliferation and invasion in surrounding parenchyma." (PMID 30853898, 2019). "In glioma-bearing immunocompetent animals, spleno- and lymphadenomegaly are observed upon infection with minute virus of mice (an autonomous protoparvovirus closely related to H-1PV), together with increased interferon-gamma (IFN-γ) production in spleen and tumor-draining lymph nodes." (PMID 29244745, 2017). "Both M-CSF and GM-CSF/IFNγ differentiated CAR macrophages and led to a glioma cell reduction of up to 30%, whereas control CARΔ(CD3ζ)-expressing macrophages reduced glioma cell numbers to a lesser extent." (PMID 39889712, 2025).
glioma (continued). "The cytokine-cytokine receptor pathway featured 35 genes (p = 3.79 × 10−7), such as CCL5, CXCL10, and IFNG, indicating impaired chemokine-mediated immune cell recruitment (e.g., CD8+ T cells and macrophages) in the immunosuppressive glioma microenvironment." (PMID 40406701, 2025). "We also found that immune responses, such as the response to bacteria and interferon-gamma signaling, are highly activated in the hypoxia regions in HG2, located in the marginal areas of high-grade glioma." (PMID 39257581, 2024). "Fucoidan suppressed tumor necrosis factor-alpha (TNF-alpha)- and interferon-gamma (IFN-gamma)-induced NO production and iNOS expression in C6 glioma cells." (PMID 39744139, 2024). "Using ELISAs and media from our primary mouse glioma cell lines cultured alone or cocultured with naïve CD8+ T cells, we assessed the production of proinflammatory cytokines IL-2, IFNγ, and TNFα." (PMID 39601621, 2024). "Abrogated USP7 expression promotes CD8+ T cell proliferation, elevates tumor necrosis factor (TNF) alpha and interferon gamma (IFN-γ) levels, and inhibits glioma cell immune evasion, which can be reversed by PD-L1 overexpression." (PMID 37415977, 2023). "Interestingly, high GPX8 expression is correlated positively with the hedgehog and kras signaling pathways and negatively with G2 checkpoint, apoptosis, reactive oxygen species (ROS) pathway, and interferon gamma pathway, which could be beneficial for the proliferation of glioma cells." (PMID 36052280, 2022). "High DDR score gliomas exhibited the enrichment of multiple immune activation pathways including IL-6/JAK/STAT3 pathway, interferon-gamma response, inflammatory response, and antigen processing and presentation." (PMID 35720326, 2022). "Use of adenovirus expressing TNFα or IFNγ into tumors enhanced infiltration of CD4+ and CD8+ T cells along with increased expression of MHCI/II on the glioma cells in vivo." (PMID 33790740, 2021). "Therefore, we tested 2 FDA-approved DNMTi, azacitidine (AZA) and decitabine (DAC), in the pediatric high-grade glioma cell line, PBT-05FHTC, which expresses relatively low baseline levels of MHC I. Interferon-gamma (IFNɣ) was used as a positive control." (PMID 41541220, 2026). "To study whether the effector functions of glioma-infiltrating CD8+ T cells are restored upon RGD + aPD-1 treatment, we quantified the production of IFNγ by T cells stimulated ex vivo with PMA and ionomycin." (PMID 40281508, 2025). "To evaluate the correlation between IFNγ secretion as measured by either ELISpot, ELF or by using FCM, we used the data from the four sets of samples evaluated in parallel by FCM and ELISpot (CRC, HD, and two glioma samples from different time points)." (PMID 36765532, 2023). "The background (no peptides) IFNγ responses, summed from all three sets of the glioma patient’s PBMC, measured 0.78% ± 1.05% for CD4+ T cells and 0.016% ± 0.02% for CD8+ T cells." (PMID 36765532, 2023). "Regarding the role and biological processes of CTSB in gliomas, we found that CTSB is mainly related to signal transduction, immune and inflammatory response, regulation of immune response, leukocyte migration, interferon-gamma-mediated signaling pathway, antigen processing and presentation." (PMID 35277559, 2022). "Recently, we have reported that in the glioma microenvironment, levels of IL4, IL13, IL10, and TGFβ are increased by the IFNG response, which constitute a regulatory network of inflammatory responses and ultimately drives macrophages toward M2-type polarization." (PMID 35492352, 2022). "Minimal differences were noted in IFNγ, TNFα, Granzyme B, and CD107B expression when comparing CD4+ T cells from glioma patients before and after M032 treatment; however, a significant reduction in IL-4 production between pre- and post-M032 treatment in peripheral blood CD4+ T cells was noted." (PMID 35342877, 2021).
glioma (continued). "Interestingly, we found reduced IFNγ expression and increased PDL1 signal in gliomas of Ccr2-/- mice that indicated a rather immunosuppressive milieu in these tumors." (PMID 32668709, 2020). "IFNγ and TNF-α were produced when TGFβ-trapped CAR-Ts recognized target glioma cells." (PMID 32974124, 2020). "PIGAS suppressed LPS/IFNγ-induced iNOS and COX-2 expression in astrocytic C6 glioma cells." (PMID 30477223, 2018). "The tumor cells are no longer shielded from host immune system, and consequently, the proinflammatory Th1 cytokines, such as IFNγ, may recruit adaptive CD4+ and CD8+ lymphocytes to the tumor site to instigate an anti-glioma immunity." (PMID 24827739, 2014). "We hypothesized that DC vaccination would activate and expand glioma-specific T cells whose recall response to gamma chain survival cytokines and/or TH1-type cytokines, such as interleukin 2 (IL-2) and interferon gamma (IFN-γ), would be enhanced." (PMID 24883189, 2014). "In addition, a Kaplan–Meier (KM) survival analysis was conducted on the core genes in liver cancer, renal clear cell carcinoma, and glioma, and it was found that TNF, IL6, IFNG, and NR1H4 in liver cancer and TNF and IL1B in renal clear cell carcinoma were associated with survival prognosis." (PMID 40238193, 2025). "In this context, pro-immunogenic mediators interferon-gamma (IFN-γ), tumor necrosis factor-alpha (TNF-α), and interleukin-2 (IL-2) have been shown to be upregulated in glioma surroundings after injection of miR-124 mimics, leading to a significant anti-glioma therapeutic impact." (PMID 39007129, 2024). "GSEA enrichment analysis pinpointed the signaling pathways implicating SOCS1 in glioma patients, indicating that high SOCS1 expression in the CGGA glioma samples correlates with allograft rejection, programmed cell death, IL-6 and JAK-STAT3 signaling pathways, and interferon-gamma responses." (PMID 39654174, 2024). "Moreover, combination therapy of glioma with recombinant vaccinia virus mediated IL2 expression, resulted in significant tumor inhibition with concomitant elevation of NK, Mac-1+ and NKT cells in blood and IFNγ and TNFα expression in tumors." (PMID 33790740, 2021). "For these targets, the human glioma LN-18 cell line was used to evaluate downregulation activity due to its high expression level of IDO-1, PDL1, and TGF-β2 with or without induction by IFNγ." (PMID 28325288, 2017).
colon carcinoma (257 papers, 1987 to 2025). "High expression levels of IFNγ and PD-L1 were detected in the colon mucosa of UC and UC-associated dysplasia/colonic cancer." (PMID 38684864, 2024). "Similarly, PANoptosis can be driven by the combination of tumor necrosis factor (TNF) and IFNγ, and human colon cancer cells deficient in IRF1 are resistant to TNF plus IFNγ-induced PANoptosis." (PMID 37557956, 2023). "Gut microbiome dysbiosis leads to elevated colon tumor susceptibility with increased CD8+ IFNγ T cells in precancerous colon lamina propria but decreased CD8+ IFNγ T cells in tumor tissues, suggesting that microbial perturbations hyper stimulate CD8+ T cells to promote early TEX." (PMID 37180158, 2023). "The Cancer Genome Atlas (TCGA) database revealed that patients with colon cancer exhibiting high IFNG expression were more likely to have elevated expression of IDO1." (PMID 41129257, 2025). "IAP inhibitors synergize with IFNγ to activate the RIPK1-dependent cell death pathway in a colon cancer cell model." (PMID 40057483, 2025). "Linear regression analysis highlighted a positive correlation between IFNγ levels within colon cancer lesions and their corresponding Al concentration (p = 0.0002; R-squared = 0.78)." (PMID 39769153, 2024). "AMPK agonists restored muscle cell activity impaired by TNFα and IFNγ and partly alleviated SMW in a transplant model of colon cancer, associated with increased oxidative metabolism." (PMID 38973385, 2024). "In murine colon cancer cells challenged with IFNγ, both qPCR and WB analysis revealed increased expression of IFI35." (PMID 37380972, 2023). "First, we examined the expression of IRFs and found that, RNA expression of IRF1 and 7 was increased in both IFNγ-stimulated murine colon cancer cells." (PMID 37380972, 2023). "According to earlier research, IFNγ is critical for the stimulation of NOS2 in DLD1 (human colon cancer) cells." (PMID 37169743, 2023). "In 1997, TWEAK was first identified as a novel, highly conserved and pro-apoptotic TNF-like protein in interferon gamma (IFNg) treated human HT-29 colon carcinoma cells." (PMID 34542797, 2022). "The interferon-stimulated response element (ISRE) in the exon 1 of PIGR gene in HT-29 human colon carcinoma cells binds IRF-1 following the stimulation of IFNγ to enhance the transcription of pIgR." (PMID 35493520, 2022). "Blockade of the checkpoint receptor TIGIT (T-cell immunoglobulin and immunoreceptor tyrosine-based inhibitory motif domain) can reverse the exhaustion of tumor-infiltrating NK cells and promote IFNγ production in a colon cancer-bearing mouse model." (PMID 34385592, 2022). "In a quite similar way as described for IL-12, overexpression of IL-27 in colon cancer cells was able to trigger local IFNγ secretion, NK cell-mediated antitumor effects, and T cell-mediated tumor-specific cytotoxicity." (PMID 36428508, 2022). "MPC downregulation also inhibits the IFNγ antitumor response in colon cancer cells, while MPC overexpression promotes ROS production and increases IFNγ-induced apoptosis." (PMID 33804985, 2021). "Downregulation of MPC subunit expression via the signal transducer and activator of transcription 3 (STAT3) pathway attenuated IFNγ-mediated apoptosis of the colon cancer cells by preventing production of reactive oxygen species (ROS)." (PMID 32708919, 2020). "More recently, it was shown that colon cancer cells can reprogram cell metabolism to coordinate proper cellular response to interferon-γ (IFNγ), a cytokine that plays a pivotal role in host antitumor immunity." (PMID 32708919, 2020). "Omics studies have demonstrated that PHY906 can inhibit colon cancer growth by modulating cell apoptosis by intervening interferon-gamma production and responses to steroid hormone stimulus." (PMID 30333750, 2018).